MIR569 (microRNA 569)
Synonyms: hsa-mir-569; MIRN569
Gene: MicroRNA gene on chromosome 3 (171,106,664 to 171,106,759, reverse strand). Ensembl gene ENSG00000207963.
Gene Ontology:
Biological process: miRNA-mediated post-transcriptional gene silencing
Cellular component: RISC complex
Homologues: Orthologues: chimpanzee ptr-mir-569 (99% identical), macaque mml-mir-569 (99% identical).
Diseases named in the same sentence as MIR569 in open-access papers:
MIR569 is named in the same sentence as 1 disease in open-access papers, as found by Europe PMC text mining. Sharing a sentence is not in itself a finding about the gene and the disease.
MIR569 shares sentences with these, for which no sentence is quoted: cancer (1 paper).